CASP1 (caspase 1)
Diseases named in the same sentence as CASP1 in open-access papers (continued):
Sharing a sentence is not in itself a finding about the gene and the disease.
acute liver failure (1 paper, 2013). Rapid deterioration of liver function causing encephalopathy and coagulopathy. "caspase-1 is an activating enzyme of IL-18, and the increase of these two proteins at the same time indicated that IL-18 in acute liver failure could be activated by Caspase-1 and thus played the role of induction of apoptosis." (PMID 24312909, 2013). "It is suggested that the trend of caspase-1 and IL-18 expression in the treatment can reflect the efficacy and prognosis of ALF to some extent; therefore, caspase-1 and IL-18 are expected to be predictors and future targets of acute liver failure." (PMID 24312909, 2013).
acute monocytic leukaemia (1 paper, 2017). "Similarly, silver wires induced ROS generation, lysosomal rupture, cathepsin B, caspase-1 and IL-1β production in human acute monocytic leukaemia (THP-1) cells." (PMID 28250714, 2017).
acute promyelocytic leukemia (1 paper, 2023). An aggressive form of acute myeloid leukemia (AML), characterized by arrest of leukocyte differentiation at the promyelocyte stage, due to a specific chromosomal translocation t(15;17) in myeloid cells. "Recently, a study observed that CASP1 had lower expression in patients with acute promyelocytic leukemia (APL), mainly in relapsed patients." (PMID 37577033, 2023).
acute-on-chronic liver failure (1 paper, 2019). Acute-on-chronic liver failure (ACLF) is an extreme condition during the natural history of chronic HBV infection, with a relatively high short-term mortality. "However, the role of caspase-1 in determining the severity of acute-on-chronic liver failure (ACLF) has yet to be elucidated." (PMID 31429707, 2019).
adenosquamous carcinoma (1 paper, 2021). A carcinoma composed of malignant glandular cells and malignant squamous cells. "In addition, ACG treatment remarkably down-regulated the expression of TLR4, p-P65, NLRP3, Caspase-1 and adenosquamous carcinoma (ASC) in lung tissue." (PMID 33645621, 2021).
alcoholic liver diseases (1 paper, 2026). A disorder caused by damage to the liver parenchyma due to alcohol consumption. "Notably, increased expression of inflammasome components (IL‐1β, IL‐18, Casp1) has been documented in patients with alcoholic liver disease and is associated with hepatic injury." (PMID 41583017, 2026).
amebiasis (1 paper, 2021). A parasitic infectious disorder caused by amoebas. "Here we show that Eh in contact with macrophages and colonic epithelial cells activated caspase-1 that cleaved cullin-1/5 in a dose- and time-dependent manner that was replicated in a colonic loop model of intestinal amebiasis." (PMID 34499701, 2021).
Anorexia (1 paper, 2021). Lack of desire to eat (loss of appetite). "Caspase-1−/− mice display depressive-like behavior and anorexia together with altered gut microbiota composition after peripheral LPS administration." (PMID 33414380, 2021).
anterograde amnesia (1 paper, 2016). "Previously, we demonstrated that glyburide can block the activation of brain caspase-1 triggered by adenosine which is a key biologic in hypoxia-induced anterograde amnesia." (PMID 27563288, 2016).
anthrax infection (1 paper, 2010). An infection caused by Bacillus anthracis bacteria. "The mice were highly susceptible to spore infection when compared to their Nlrp1bS/SCasp1+/− and Nlrp1bS/SCasp1+/+ (Balb/c backcrossed, N4) littermates, implicating caspase-1 in Nlrp1bS-mediated resistance to anthrax infection." (PMID 21170303, 2010).
Aortic dissection (1 paper, 2022). Aortic dissection refers to a tear in the intimal layer of the aorta causing a separation between the intima and the medial layers of the aorta. "The Nlrp3-caspase 1 complex is activated in the condition of aortic dissection and participates in the process of aortic damage by degrading smooth muscle cell contractile protein, promoting macrophage inflammation and MMP9 expression and intensifying extracellular matrix degradation." (PMID 35211530, 2022).
arteriosclerosis (1 paper, 2015). A vascular disorder characterized by thickening and hardening of the walls of the arteries. "In addition, these data suggest that inhibition of inflammasomes, caspase-1, calpain, or IL-1α are potential therapeutic candidates to prevent arteriosclerosis and allograft rejection." (PMID 26324711, 2015).
astrocytoma (1 paper, 2025). "Interestingly, one study showed that caspase-1 mediates FAS-induced cell death in astrocytoma cells." (PMID 40512405, 2025).
autoimmune thyroiditis (1 paper, 2018). "Correlation between NLRP3, NLRP1, NLRC4, absent in melanoma 2 (AIM2), ASC, caspase-1, IL-1β, and IL-18 expression in the autoimmune thyroiditis group." (PMID 29915579, 2018).
bacterial meningitis (1 paper, 2012). Inflammation of the membranes surrounding the brain and spinal cord due to a bacterial infection. "Eleven SNPs in seven genes (TLR2, TLR4, TLR9, NOD1, NOD2, CASP1, and TRAIL) were genotyped in 393 survivors of childhood bacterial meningitis (BM) (327 MM patients and 66 PM patients)." (PMID 22662111, 2012).
Behcet’s syndrome (1 paper, 2021). "Upon in vitro stimulation of PBMC with LPS/ATP, the mRNA and protein levels of NLRP3, ASC and/or Caspase-1 were significantly up-regulated only in PBMC from active Behcet’s syndrome patients compared to healthy controls." (PMID 34572082, 2021). "Both mRNA and protein levels of NLRP3, ASC, and Caspase-1 were shown to be upregulated in PBMC and in skin lesions of patients with Behcet’s syndrome, compared to healthy controls." (PMID 34572082, 2021).
biliary atresia (1 paper, 2020). A rare, biliary tract disease characterized by progressive obliterative cholangiopathy of the intra- and extrahepatic bile ducts, occurring in the embryonic/ perinatal period, leading to severe and persistent neonatal jaundice and acholic stool. "In biliary atresia, a neonatal obstructive cholangiopathy, increased expression of NLRP3, Caspase-1 and IL-1R1 has been demonstrated in the livers of patients at the time of diagnosis." (PMID 32192118, 2020).
bipolar disorder (1 paper, 2025). A disorder of the brain that causes unusual shifts in mood, energy, activity levels and the ability to carry out day-to-day tasks. "Frontal lobe samples of patients diagnosed with bipolar disorder had higher levels of NLRP3, ASC, caspase-1, and pro-inflammatory cytokines than samples from the control group." (PMID 40002529, 2025).
bone cancer (1 paper, 2022). A primary or metastatic malignant neoplasm affecting the bone or articular cartilage. "Mounting evidence reveal that the expression of NLRP3 inflammasome, including NLRP3, apoptosis-associated speck-like protein containing a caspase activation and recruitment domain (ASC), and caspase-1, were significantly increased in a time-dependent manner in bone cancer pain." (PMID 35592413, 2022).
Bordetella pertussis Infections (1 paper, 2014). "Our vaccination results also show that IL-1 related signaling is important for protective immunity to B. pertussis and can be initiated independently from caspase-1, which has been shown to be activated by the current alum adjuvant in acellular pertussis vaccines." (PMID 25198773, 2014).
Bovine mastitis (1 paper, 2023). INFLAMMATION of the UDDER in cows. "Zophobas morio (Z. morio) hemolymph can decrease the levels of NLRP3, caspase-1 and NLRP6 and inhibit the secretion of IL-1β and IL-18, thereby attenuating E. coli- or Staphylococcus simulans (S. simulans)-induced pyroptosis; thus, it can be a new therapeutic candidate for bovine mastitis." (PMID 37845761, 2023).
bronchiectasis (1 paper, 2025). Segmental, irreversible dilation of the bronchial tree resulting in the accumulation of secretions which leads to obstruction. "To assess NLRP3 inflammasome activation, we compared sputum caspase-1 p20 expression between bronchiectasis patients and healthy controls." (PMID 41395250, 2025). "Our findings, together with prior evidence, suggest that activation of the NLRP3–caspase-1 axis in bronchiectasis neutrophils facilitates phenotypic activation and NET formation, but inflammasome signaling is not indispensable for NET release." (PMID 41395250, 2025). "NLRP3, ASC, and the active caspase-1 fragment (p20) were significantly higher in patients with bronchiectasis than in healthy controls (P < 0.05)." (PMID 41395250, 2025).
bubonic plague (1 paper, 2020). A plague in which the bacteria have infected the lymphatic system. "NLRP12 was one of the first NLR proteins described to activate pro-caspase-1 synergistically with ASC to generate pro-inflammatory signals, which occurs via TLR4 signalling and formation of an ASC-caspase-1 inflammasome in response to Yersinia pestis, the causative agent of bubonic plague." (PMID 33036374, 2020).
Burkholderia Infections (1 paper, 2018). Infections with bacteria of the genus BURKHOLDERIA. "We and others have previously shown that processing and secretion of the mature form of IL-1β and IL-18 in response to Burkholderia infection was dependent on caspase-1." (PMID 29791511, 2018). "Caspase-1 has been shown to be protective against Burkholderia infections." (PMID 29791511, 2018). "Recently it has been proposed that in the early phase of Burkholderia infection caspase-11 may act as an IFNγ-inducible effector mechanism because of its reliance on the IL-18-IFNγ axis for priming, which would place non canonical inflammasome downstream of canonical caspase-1 activation." (PMID 29791511, 2018).
C. perfringens infection (1 paper, 2019). "To clarify how LPS priming affects inflammasome activation in cells with C. perfringens infection, we examined the activation level of caspase-1 and IL-1β in the infected BMDMs primed or not primed with LPS." (PMID 31708887, 2019). "Similar as C. perfringens infection, no caspase-1 activation was detected (data not shown)." (PMID 31708887, 2019).
celiac disease (1 paper, 2019). An autoimmune genetic disorder with an unknown pattern of inheritance that primarily affects the digestive tract. "In conclusion, we propose that p31-43 plays a central role in the pathogenesis of Celiac disease at least in part via an intrinsic ability to form oligomers of polyproline II-like structures that self-assemble and drive an NLRP3-caspase 1 dependent innate immune response in the intestinal mucosa." (PMID 30761127, 2019).
cerebral aneurysm (1 paper, 2021). "Especially, we further observed participation of BCL-2-mediated apoptosis pathway and caspase-1 related pyroptosis in the development of cerebral aneurysm and aneurysmal subarachnoid hemorrhage in corresponding transcriptomes." (PMID 34895131, 2021).
cerebral edema (1 paper, 2022). "Accumulating evidence have shown caspase-1 activation plays pivotal roles in exacerbating cerebral edema and increasing the occurrence of HT via loosening BBB integrity." (PMID 35370546, 2022). "Similarly, heme and iron can both generate mitochondrial ROS, activate NLRP3/caspase-1 pathway, and lead to BBB hyperpermeability and cerebral edema, specifically on ECs, which can be alleviated by iron chelator deferoxamine." (PMID 35370546, 2022). "The reduction of AIM2 inflammasome and caspase-1 expression via cyclic GMP–AMP synthase antagonist A151, NLRP6 reduction via NLRP6 siRNA, and restraining NLRC4 activation via RGS2 all show the attenuation of cerebral edema." (PMID 35370546, 2022).
cerebral small vessel disease (1 paper, 2025). Cerebral small vessel disease is the term currently used to pathological processes that affect the brain parenchymal circulation (arterioles, capillaries, and veins). "Cerebral small vessel disease (CSVD) may benefit from anti-inflammatory therapy, as age-related inflammation—mediators such as TNF, caspase-1, IL-1β, and the NLRP3 inflammasome—is considered a risk factor." (PMID 40017533, 2025).
cherubism (1 paper, 2025). Cherubism is a rare, self-limiting, fibro-osseous, genetic disease of childhood and adolescence characterized by varying degrees of progressive bilateral enlargement of the mandible and/or maxilla, with clinical repercussions in severe cases. "This study focuses on the consequences of Caspase-1 deletion leading to IL-1β alterations in the pathogenesis of cherubism." (PMID 39951467, 2025). "Taken together, these results seem to indicate that our hypothesis of NLRP3/Caspase-1 involvement in the pathogenesis of cherubism is incorrect." (PMID 39951467, 2025).
chorioamnionitis (1 paper, 2019). A morphologic finding indicating inflammation of the fetal sac membranes. "Furthermore, umbilical cord blood monocytes from preterm infants with histological chorioamnionitis showed reduced caspase 1 activity compared to those without histological chorioamnionitis." (PMID 30873043, 2019).
chromoblastomycosis (1 paper, 2025). "In conclusion, the present data demonstrate, for the first time, that the inflammasome is activated and that NLRP3 and caspase-1 mediated the F. pedrosoi-induced production of IL-18, which promotes the Th-1-mediated immune response during chromoblastomycosis." (PMID 40315193, 2025). "Previously, our group showed that IFN-γ is an important cytokine involved in immune defenses during chromoblastomycosis; therefore, we speculated that IFN-γ could play a role in the central mechanism regulated by caspase-1 after F. pedrosoi infection." (PMID 40315193, 2025).
chronic gastritis (1 paper, 2025). Inflammation of the stomach that is chronic in nature. "CAG mice infected with Helicobacter were given Chaenomeles speciosa total triterpenoids, and their chronic gastritis and atrophy glands were improved by the reduction of thioredoxin-interacting protein (TXNIP), NLRP3, pro-caspase-1, and caspase-1 levels." (PMID 40264171, 2025).
chronic hepatitis B (1 paper, 2015). "In this study, the expression AIM2, and its downstream cytokines, caspase-1, IL-18 and IL-1β, in liver tissue of patients with chronic hepatitis B and C (CHB, CHC) were investigated." (PMID 26290184, 2015).
chronic myelomonocytic leukemia (1 paper, 2020). A myelodysplastic/myeloproliferative neoplasm which is characterized by persistent monocytosis, absence of a Philadelphia chromosome and BCR/ABL fusion gene, fewer than 20 percent blasts in the bone marrow and blood, myelodysplasia, and absence of PDGFRA or PDGFRB rearrangement. "Regarding increased pro-inflammatory signaling, one publication reported the oncogenic KRASG12D mutation as a driver for elevated myeloproliferation and chronic myelomonocytic leukemia (CMML) through activation of the NLRP3 inflammasome and caspase-1-mediated cleavage of pro-inflammatory cytokines." (PMID 32604862, 2020).
coagulopathy (1 paper, 2025). "IL-1β and the inflammasome may play some role in this process, as mice deficient in caspase-1 have shown reduced markers of coagulopathy and inflammation after STm infection." (PMID 40064845, 2025).
conjunctivitis (1 paper, 2023). Inflammation of the conjunctiva of the eye. "Here, the NLRP3 inflammasome is a major driver in releasing pro-inflammatory factors such as IL-6 and caspase-1, leading to follicular conjunctivitis and bulbar congestion, even as isolated signs in the ‘asymptomatic’ patient." (PMID 37764042, 2023).
coronary atherosclerosis (1 paper, 2024). Atherosclerosis of the coronary vasculature. "Overexpressed caspase-1 has been demonstrated in the aortas of patients with coronary atherosclerosis." (PMID 39074125, 2024).
crescentic glomerulonephritis (1 paper, 2011). A histopathologic term for a pattern of diseases characterized by extensive crescent formation in the glomeruli; patients present clinically with rapid deterioration of renal function, and possible progression to end-stage renal failure within weeks or months. "We therefore conclude that GBM antiserum induces crescentic glomerulonephritis independent of the NLRP3 inflammasome and of ASC-mediated activation of caspase-1." (PMID 22046355, 2011).
Crush Syndrome (1 paper, 2025). Severe systemic manifestation of trauma and ischemia involving soft tissues, principally skeletal muscle, due to prolonged severe crushing. "Pathologically, it contributes to crush syndrome-induced kidney injury via myoglobin-triggered M1 macrophage polarization through the RIG-I/Caspase-1/GSDMD axis, demonstrating its multifaceted roles in immunity and disease." (PMID 40491921, 2025).
delirium (1 paper, 2026). A disorder characterized by confusion; inattentiveness; disorientation; illusions; hallucinations; agitation; and in some instances autonomic nervous system overactivity. "This protective effect may be associated with the observed sustained downregulation of the peripheral NLRP3/caspase-1/IL-1β signaling pathway, which consequently weakens the link between early postoperative inflammation and delirium." (PMID 41998765, 2026).
demyelination (1 paper, 2023). "Similarly, we found caspase-1, GSDMD, NLRP3 and IL-1β mainly localize in microglia, suggesting microglia as the dominating cell type that undergo pyroptosis in our LPC-induced demyelination model." (PMID 36803990, 2023).
diabetic neuropathy (1 paper, 2022). A chronic, pathological complication associated with diabetes mellitus, where nerve damages are incurred due to diabetic microvascular injury involving small blood vessels that supply these nerves, resulting in peripheral and/or autonomic nerve dysfunction. "The results showed that JMT reduced the levels of mRNA and NLRP3 protein; also, the expression of IL-1β and caspase-1 in the spinal cord of diabetic neuropathy decreased." (PMID 35655729, 2022).
dissection (1 paper, 2021). The separation and isolation of tissues for surgical purposes, or for the analysis or study of their structures. "Both smooth muscle actin degradation and the incidence of aortic dissections was reduced in Nlrp3 and caspase-1 knockout mice, as well as by treatment with glyburide, which is an antidiabetic drug incidentally inhibiting Nlrp3–caspase-1 inflammasome complex formation." (PMID 34572082, 2021).
dopaminergic neuroblastoma (1 paper, 2020). A neuroblastoma associated with increased dopamine excretion. "Caspase-1 has also been demonstrated to selectively cleave parkin at Asp 126 residue and inactivate the function of the ubiquitin-like domain in Chinese hamster ovary and human dopaminergic neuroblastoma SH-SY5Y cells." (PMID 32787872, 2020).
dysferlinopathy (1 paper, 2025). "Supporting the relevance of inflammasome activation in dysferlinopathy, previous studies have shown increased levels of NLRP3, ASC, active caspase-1, and mature IL-1β in skeletal muscles from dysferlin-deficient (A/J) mice." (PMID 41155239, 2025).
Dyskinesia (1 paper, 2020). A movement disorder which consists of effects including diminished voluntary movements and the presence of involuntary movements. "MPTP/p treatment elevates expression of caspase-1 in the mouse midbrain, whereas caspase-1 knockout ameliorates DA neuronal loss and dyskinesia induced by MPTP/p." (PMID 32792920, 2020).
endometrial disorder (1 paper, 2025). A non-neoplastic or neoplastic disorder that affects the endometrium. "Given the key role of the NLRP3 inflammasome in inflammatory endometrial disorders, we investigated the expression of NLRP3 and its downstream effectors, including ASC, Caspase-1, and GSDMD, following exposure to T. pyogenes and MVs." (PMID 40691648, 2025).
endophthalmitis (1 paper, 2021). An infectious process affecting the internal structures of the eye. "Additionally, genes encoding pro- and antiapoptotic/pyroptosis molecules were found to be differentially regulated in MDR-PA-induced endophthalmitis and included upregulation of caspase-1, caspase-4, and caspase-8." (PMID 35046947, 2021).